NRL (neural retina leucine zipper)
Diseases named in the same sentence as NRL in open-access papers (continued):
Sharing a sentence is not in itself a finding about the gene and the disease.
tumor (8 papers, 2015 to 2024). "Both JUN and NRL were included in the GO terms related to development, prompting us to speculate that sunitinib may promote tumor differentiation via inactivation of MAPK activity in RB654 organoids." (PMID 36726110, 2023). "Both photoreceptor lineage genes are required for tumor maintenance and the antiapoptotic BCL-XL protein, a direct target of the NRL gene, is required for tumor cell survival; the targeting of BCL-XL could represent a biochemical vulnerability of this medulloblastoma subset." (PMID 30279357, 2018). "Both genes are required for tumor maintenance while the target of NRL, the protein BCL-XL, is necessary for tumor cell survival." (PMID 30876441, 2019). "In addition, the expression levels of rod-enriched genes, including NRL, NR2E3, CNGA1, and PDE6G, were depleted in organoids, consistent with tumor, but high in normal retina, where rods outnumber cones." (PMID 30353124, 2018).
cancer (7 papers, 2011 to 2025). A tumor composed of atypical neoplastic, often pleomorphic cells that invade other tissues. "Despite a few steps that have been taken in exploring the function and mechanism of NRL in cancer proliferation and apoptosis, more research is necessary to fully understand the link between NRL and cancer." (PMID 36750911, 2023). "It is previously reckoned that NRL has not been implicated in human cancer, and it is solely viewed as a terminal differentiation factor of rod photoreceptors." (PMID 36750911, 2023). "NRL directly protects cancer cells from apoptosis by transcriptionally inducing BCL-XL expression." (PMID 36750911, 2023). "Since epidemiologic studies closely link prolactin and the development of ERα+ tumors in women, we examined characteristics of the aggressive ERα+ and ERα- carcinomas which develop in response to mammary prolactin in a murine transgenic model (neu-related lipocalin- prolactin (NRL-PRL))." (PMID 21276249, 2011). "Moreover, only a few studies exist regarding the role of NRL in cancer." (PMID 36750911, 2023). "NRL might be a circulatory marker reflecting increased cancer aggressiveness." (PMID 33817142, 2019). "During retinal development, OTX2 occupies a pivotal position in a photoreceptor gene hierarchy, including basic leucine zipper TFs NRL and CRX, both overexpressed in G3 MB, where they promote cancer survival via the anti-apoptotic factor BCL2L1." (PMID 41198629, 2025). "OTX2 and other photoreceptor TFs, including NRL and CRX, drives anti-apoptotic factors like BCL2L1, linking this gene program to sustained cancer cell viability." (PMID 41198629, 2025). "Specifically, we examined the expression of Akt1m in primary cancers from BRCA1 conditional knockout mice (Brca1-/-), PtenG129E mutant females as well as transgenic mice that overexpress ERBB2 (MMTV-neu) and prolactin (NRL-PRL)." (PMID 24628780, 2014). "Interestingly, signals through this pathway are required for initiation, but not progression, of PRL-induced cancers in NRL-PRL females." (PMID 28103936, 2017). "Nonparous NRL-PRL females develop mammary pathology that exhibits many features of human disease, including early lesions (hyperplasias and intraepithelial neoplasias, similar to ductal carcinoma in situ in women), and eventually, ERα+ and ERα- carcinomas." (PMID 21276249, 2011).
retinopathies (6 papers, 2007 to 2026). "Continued expression of NRL is essential for maintaining rod function, and mutations affecting NRL activity are associated with retinopathies." (PMID 40047526, 2025). "Continued expression of NRL is essential for maintaining rod function 20, and mutations affecting NRL activity are associated with retinopathies 21–24." (PMID 39345562, 2025). "Mutations in the human NRL gene are associated with autosomal dominant retinitis pigmentosa (adRP) and other retinopathies." (PMID 17653056, 2007). "Mutations in NRL are associated with retinopathies; many of these are suggested to change phosphorylation status and alter NRL-mediated transactivation of rhodopsin promoter." (PMID 17653056, 2007). "Mutations in NRL, its targets, and interacting proteins are associated with retinopathies." (PMID 42246540, 2026). "As inhibition of MAPK signaling pathways decreases NRL-mediated transactivation of rhodopsin promoter, we propose that phosphorylation changes associated with NRL mutations perturb gene expression in rods, leading to photoreceptor degeneration in retinopathies." (PMID 17653056, 2007). "NRL, CRX, and NR2E3 are key transcription factors that regulate photoreceptor differentiation, and mutations in these lead to retinopathies." (PMID 19898638, 2009). "Our data reveals the role of NRL Pro-51 as an authentic MAPK2-dependent phosphorylation site, which when mutated in retinopathy patients affects the downstream transcriptional regulatory functions of NRL." (PMID 17653056, 2007). "The current signed-off version of Genomics England’s PanelApp Retinal Disorders virtual panel gene list (version v2.195) includes all six main CACD genes, plus CRX, NR2E3, NRL, RAX2 and also VSX2, but as low-evidence gene (red list)." (PMID 35656327, 2022).
cardiovascular disease (1 paper, 2023). "Our findings also show that the NRL ratio, a marker of systemic inflammation that is closely linked to cardiovascular disease, is much greater in individuals with both co-morbidities." (PMID 37370012, 2023).
NRL also shares sentences with these, for which no sentence is quoted: pigmentary retinal degeneration (2 papers); acute kidney injury (1); autosomal recessive retinitis pigmentosa (1); congenital nystagmus (1); end-stage renal disease (1); infection (1); Leber congenital amaurosis (1); liver cancer (1); lung adenocarcinoma (1); lung carcinoma (1); preeclampsia (1); Sepsis (1); Strabismus (1); Visual impairment (1).